MCL1 (MCL1 apoptosis regulator, BCL2 family member)
Diseases named in the same sentence as MCL1 in open-access papers (continued):
Sharing a sentence is not in itself a finding about the gene and the disease.
melanoma (continued). "In summary, the present studies show that both BH3 mimetics induce strong ER stress responses in melanoma cells, which limit the induction of apoptosis due principally to ER stress-induced upregulation of the anti-apoptotic protein Mcl-1." (PMID 24367627, 2013). "Inhibition of Mcl-1 and A1 resulted in cell death of melanoma cell lines and targeting both antiapoptotic Bcl-2 proteins simultaneously enhanced cell death to 80% whereas non-malignant cells remained unaffected." (PMID 22292048, 2012). "In melanoma cells, however, significant apoptosis induction was observed when Mcl-1 or A1 were inhibited: Cell death increased from 8% in control siRNA-treated cells to 40% in Mcl-1-inhibited or 30% in A1-inhibited cells." (PMID 22292048, 2012). "In 1205Lu melanoma cells, cell death induction was observed throughout most combinations, which was expected since inhibition of Mcl-1 or A1 alone already resulted in cell death." (PMID 22292048, 2012). "In melanoma cell lines, substantial sensitivity to Mcl-1 inhibition was observed in 3 of 5 melanoma cells, i.e., WM3211, WM1232, and WM1158 (other panels)." (PMID 22292048, 2012). "Together, the results show that the combined inhibition of Mcl-1 and A1 efficiently induces apoptosis in melanoma cell lines, whereas primary cells remain unaffected." (PMID 22292048, 2012). "Our previous studies found that 12 markers including pAkt, Bim, BRG1, BRMS1, CTHRC1, Cul1, ING4, MCL1, NQO1, SKP2, SNF5 and SOX4 were associated with melanoma progression." (PMID 23028750, 2012). "Among the tumor-specific combinations, simultaneous inhibition of Mcl-1 and A1 most efficiently induced cell death in 1205Lu melanoma cells." (PMID 22292048, 2012). "This specific sensitivity of melanoma cells was further enhanced by the combined inhibition of Mcl-1 and A1 and resulted in 60% to 80% cell death in all melanoma cell lines tested." (PMID 22292048, 2012). "Other studies reported that melanoma cells require Mcl-1 for survival under certain stress conditions, like endoplasmatic reticulum stress, lack of cell adhesion, or proapoptotic stimuli that target the death receptor-mediated apoptotic pathway." (PMID 22292048, 2012). "A similar oncogenic role for miR-149 was also seen in melanoma in which upregulation of miR-149 causes downregulation of GSK3-α and upregulation of Mcl-1, resulting in apoptotic resistance." (PMID 23144691, 2012). "We have addressed these questions in the A375 melanoma model showing that A375 cells, in vivo, down-regulate pro-death bax expression, and up-regulate anti-death bcl-2, bcl-xl, and mcl-1 relative to cells cultured in vitro." (PMID 22233801, 2012). "Mcl-1 is a member of the Bcl-2 family of proteins, which has been shown to play a critical role in the survival of malignant cells, including melanoma." (PMID 23166634, 2012). "On day 3, melanoma cell viability was decreased by inhibition of A1 and Mcl-1, respectively, and – most prominently – by inhibition of both." (PMID 22292048, 2012). "The results suggested that targeting of the appropriate Bcl-2 proteins, i.e., Mcl-1 or A1, represents a strategy to specifically induce apoptosis in melanoma." (PMID 22292048, 2012). "This demonstrates that - even in the presence of varying expression levels and sensitivities among melanoma cell lines - targeting of A1 at least broadens the apoptotic sensitivity of melanoma cells to Mcl-1 inhibition." (PMID 22292048, 2012). "We have previously shown that by treating melanoma cells with 9.2.27PE, the Mcl-1 protein level is rapidly decreased due to its short half-life." (PMID 21915275, 2011). "Numerous additional in vitro studies for both melanoma and other cancer cells have shown that the Mcl-1/Noxa ratio is critical for determining resistance or sensitivity to ABT-737." (PMID 21897876, 2011).
melanoma (continued). "Our data were consistent with studies on other tumor types, such as melanoma, myeloma and malignant pleural mesothelioma, in which the specific downregulation of Mcl-1 has been shown to sensitize cancer cells to proteasome inhibitor-induced apoptosis." (PMID 22078414, 2011). "Much like Mcl-1, Noxa is another Bcl-2 family protein that is strongly increased by proteasome inhibition in different cancers, including melanoma and multiple myeloma." (PMID 21170316, 2010). "Mcl-1 expression increases with tumor depth and stage suggesting that Mcl-1 is a critical obstacle to apoptosis induction in melanoma." (PMID 19684859, 2009). "A number of studies have reported overexpression of Bcl-2, Mcl-1 and Bcl-xL in melanoma compared to normal tissue or benign nevi, although there is some controversy as to the role of Bcl-2 expression in chemoresistance." (PMID 19684859, 2009). "Knockdown of the BH3-family protein Mcl-1 using shRNA sensitised the melanoma cells to U0126-induced apoptosis, showing that overexpression of these key anti-apoptotic proteins in melanoma is a critical barrier to an effective BRAF/MEK inhibitor therapy." (PMID 19156138, 2009). "In a previous study from our group, we reported increased expression of Mcl-1 in malignant melanoma compared to benign nevi in an immunohistochemical comparison of 5 nevi and 15 melanoma samples (10 primary and 5 metastases)." (PMID 19684859, 2009). "Our group was one of the first to describe increased expression of the anti-apoptotic protein Mcl-1 in melanoma." (PMID 19684859, 2009). "Mechanistically, it seems that combined MEK/mTOR inhibition reduces the expressions of Mcl-1 and Bcl-2, two proteins that are known to suppress apoptosis induction in melanoma cells." (PMID 19156138, 2009). "We therefore sought to identify factors that modify sensitivity of melanoma cells to the combination treatment of Mcl-1 DsiRNA and ABT-737." (PMID 19684859, 2009). "Our findings suggest that the combination of ABT-737 and Mcl-1 knockdown represents a promising, new treatment strategy for malignant melanoma." (PMID 19684859, 2009). "Here we present evidence that the combination of ABT-737 and Mcl-1 knockdown by DsiRNA efficiently induces cell death in multiple melanoma cell lines well over the effect seen with the individual treatments." (PMID 19684859, 2009). "Further elucidation of the apoptotic pathways involved in treatment response will aid in the effective implementation of an ABT-737 and Mcl-1 knockdown-based therapy in malignant melanoma." (PMID 19684859, 2009). "Here we report that knockdown of Mcl-1 greatly reduces cell viability in combination with ABT-737 in six different melanoma cell lines." (PMID 19684859, 2009). "In particular, resistance to MAPK inhibition based on high levels of antiapoptotic Bcl-2 proteins was overcome in melanoma cells by another small molecule BH3 mimetic (TW-37) developed by computer modeling for binding to Mcl-1, Bcl-xL and Bcl-2." (PMID 19506730, 2008). "Our data also add to studies on other tumor types such as malignant melanoma and sarcoma, in which specific downregulation of Mcl-1 has been shown to sensitize cancer cells to chemotherapeutic drug-induced apoptosis." (PMID 17014711, 2006). "Finally, ectopic overexpression of MCL1 induces mTORC1 activation in melanocytes and the levels of MCL1 overexpression correlate tightly with mTORC1 signaling activity in melanoma patient samples." (PMID 41326406, 2025). "In melanoma cells, MCL1 depletion led to a decline in cell viability on longer term." (PMID 41326406, 2025). "Finally, we inoculated mice in both flanks with either control melanoma cells transduced with doxycycline-inducible scrambled shRNA or shRNA against MCL1." (PMID 41326406, 2025).
melanoma (continued). "This is consistent with previous studies showing that the co-inhibition of Mcl-1 and other anti-apoptotic proteins, such as Bcl-xL, can significantly induce apoptosis and cell death of melanoma cell lines or sensitize glioma stem cells to other Bcl-2 inhibitors." (PMID 40707448, 2025). "To establish the preclinical therapeutic potential of the MCL1 inhibitor S64315 in melanoma, we began our investigation by comparing the efficacy of this agent in both immunocompromised nude mice, which lack functional lymphocyte populations, and immunocompetent C57BL/6 J mice." (PMID 38459020, 2024). "Indeed, we found that the combination of the MCL1 inhibitor S64315 and anti-PD-1 decreased melanoma tumor growth further, compared to anti-PD-1 alone." (PMID 38459020, 2024). "Specifically, a pre-clinical study in BRAFV600E melanoma demonstrated synergistic induction of apoptosis when BRAF or MEK inhibitors were combined with a MCL-1 inhibitor, which aligned with MCL-1 being the predominant pro-survival protein expressed in melanoma cells." (PMID 38429301, 2024). "Mcl-1 downregulation in melanoma cells was also seen in response to some other pro-apoptotic strategies, including treatment with TRAIL (TNF-related apoptosis inducing ligand) in combinations with kinase inhibitors such as vemurafenib, indirubin, or BMS-345541." (PMID 38542429, 2024). "Moreover, YAP overexpression promotes anoikis resistance in melanoma cells and metastasis in in vivo experiments, through the expressions of downstream genes Bcl-2 and Mcl-1." (PMID 38755629, 2024). "Mcl-1, a prosurvival protein, is a crucial member of the Bcl-2 family and has been shown to be overexpressed in various cancer types, including ovarian, cervical, hepatocellular, pancreatic, non-small cell lung, and testicular germ cell cancers and melanomas." (PMID 39272918, 2024). "Indeed, significant expression of both Bcl-2, Bcl-xL, Mcl-1, and Bcl-w is characteristic in melanoma cell lines." (PMID 38542429, 2024). "Using both in vitro and in vivo studies, with human and mouse samples, as well as analyses of a public clinical survival data dataset, this study provides strong evidence for a novel use of the MCL1 inhibitor S64315 to enhance the efficacy of immunotherapies against melanoma." (PMID 38459020, 2024). "Thus, we investigated the effects of ABT-737 and ABT-263, which target Bcl-2, Bcl-xL and Bcl-w as well as the Bcl-2-selective ABT-199 and the Mcl-1-selective S63845, in a panel of four BRAF-mutated and BRAF-WT melanoma cell lines." (PMID 38542429, 2024). "Moreover, oleocanthal downregulates the expression of antiapoptotic protein such as Bcl-xL, Mcl-1, Bcl-2, survivin in melanoma and hepatocarcinoma cells." (PMID 39203892, 2024). "Many solid cancers upregulate MCL1, and melanoma in particular is dependent on MCL1 for survival." (PMID 38459020, 2024). "This indicates that Mcl-1 inhibition alone cannot be sufficient for treatment of melanoma." (PMID 36902392, 2023). "This means that the treatment with MCL-1 inhibitor might be more beneficial for melanoma patients who developed resistance to MEK inhibitors than for patients before the treatment with MEK inhibitors." (PMID 37835493, 2023). "Indeed, Mcl-1 overexpression conferred resistance to vemurafenib or D/T combination in melanoma cells." (PMID 37834284, 2023). "Our findings also suggest that the treatment with MCL-1 inhibitors might be more beneficial for melanoma patients who developed resistance to MEK inhibitors than patients before this treatment." (PMID 37835493, 2023).
melanoma (continued). "Therefore, the next question was how resistant melanoma cells displaying different pro-survival capacity would respond to agents affecting the anti-apoptotic activity of MCL-1." (PMID 37835493, 2023). "In conclusion, combined inhibition of ERK and Mcl-1 revealed an impressive efficacy both in BRAF-mutated and WT melanoma cells, and may thus represent a new strategy for overcoming drug resistance." (PMID 36902392, 2023). "Phosphorylation of histone H2AX on serine 139 (γ-H2AX), which was upregulated in those S63845-treated melanoma cell populations that displayed high percentages of Annexin V-positive cells suggests that apoptosis induced by the MCL-1 inhibitor was accompanied with the DNA damage." (PMID 37835493, 2023). "Previously, applying both in silico and in vitro experimental models, we demonstrated that interaction between ciprofloxacin and MITF and Mcl-1 could affect viability and apoptosis of melanoma cells." (PMID 36045272, 2022). "Moreover, it was shown that the use of MIM1-high and specific Mcl-1 inhibitor increased the level of Mcl-1 protein in BRAF-mutant amelanotic C32 melanoma cells with subsequent apoptosis induction." (PMID 36045272, 2022). "MCL-1 in combination with BCL-XL represents a promising target in melanoma." (PMID 36365208, 2022). "Hosseini’s research results showed that PG had a great affinity for the anti-apoptotic member MCL-1 of the BCL-2 family, and it could activate the mitochondrial apoptosis pathway by destroying the MCL-1/BAK complex to cause apoptosis in melanoma cells." (PMID 36364107, 2022). "By targeting the anti-apoptotic modulators (BCL-XL and MCL-1) of melanoma, this combination could provide a new therapeutic efficacy against metastatic melanoma resistant to ongoing treatment." (PMID 34575429, 2021). "However, the situation in melanoma resembles TET since MCL-1 and BCL-xL are considered the main pro-survival factors." (PMID 34781947, 2021). "However, transfection with miR-1469 resulted in an inhibitory effect on MCL1 protein expression that was variable, depending on the melanoma cell line examined." (PMID 34469478, 2021). "In summary, our data indicate that the combination of MCL1 inhibitor with AZA may be a viable option for melanoma patients." (PMID 34451846, 2021). "In order to determine this, the expression of MCL1 following miR-1469 transfection of melanoma cell lines was assessed by immunoblot to determine whether it may function as a target gene in the context of melanoma." (PMID 34469478, 2021). "According to our previous data showing that silencing of Mcl-1 sensitizes melanoma cell lines to TRAIL, we hypothesized that Mcl-1 silencing may also increase the cytotoxicity of AdV-TRAIL in melanoma cells." (PMID 34028599, 2021). "The reduction in metabolic plasticity via intermittent fasting to limit glucose availability (and therefore glycolysis) and metformin (an inhibitor of oxidative phosphorylation) led to decreases in tumor growth in mice with melanoma xenografts via lowered MCL1 expression." (PMID 34831420, 2021). "Here, we investigated whether the cytotoxicity of AdV-TRAIL, an oncolytic adenovirus, which expresses TRAIL after induction by doxycycline (Dox), can be improved in melanoma cells by silencing of Mcl-1." (PMID 34028599, 2021). "Additionally, although MCL1 is a defined target gene of miR-1469 that holds clinical significance in the context of melanoma, the results of this study demonstrate that MCL1 expression is modestly impacted by miR-1469 alone in the melanoma cell lines examined." (PMID 34469478, 2021). "Increasing the cytotoxicity of AdV-TRAIL by silencing of Mcl-1 may have relevance for further employment of the virus in melanoma therapy." (PMID 34028599, 2021). "Overall, this indicates that the matrix isoform of MCL1 could play a role in enhancing oxidative phosphorylation in the metabolism of melanoma cells." (PMID 34831420, 2021).
melanoma (continued). "Targeting of Mcl-1 may therefore contribute to a more effective treatment of melanoma using TRAIL-expressing oncolytic adenovirus." (PMID 34028599, 2021). "In melanoma, the apoptotic machinery is dependent in part on MCL1." (PMID 34451846, 2021). "Given its increased expression in melanoma and its confirmation as a gene target for miR-1469 in laryngeal cancer, we assessed whether MCL1 may also function as a target gene in the context of melanoma." (PMID 34469478, 2021). "Thus the potentiation of apoptosis induced by co-inhibition of BCL2 and MCL1 is a strategy with wide applicability to enhance the anti-melanoma activity by targeted therapies in malignant melanoma." (PMID 34331013, 2021). "Our in vitro and in vivo data showed that the simultaneous targeting of BCL2 and MCL1 is effective in treating advanced melanoma, and this combination is more potent in melanomas without the BRAF-V600E/K variant." (PMID 32764384, 2020). "Thus, our data along with current clinical trials provide the framework for testing the efficacy of the combination of MCL1 inhibitors with BCL2 inhibitors in melanoma patients." (PMID 32764384, 2020). "We tested the treatment efficacy of combining MCL1 inhibitors with ABT-199 in melanomas with or without BRAF-V600 hotspot mutations (MUT vs WT groups)." (PMID 32764384, 2020). "Therefore, this study can serve as the starting point for clinical trials that combines MCL1 inhibitors with BCL2 inhibitors for patients with advanced melanoma." (PMID 32764384, 2020). "At the same time, downregulation of Bcl-2, Bcl-xL and Mcl-1 by (+)-bornyl p-coumarate may induce autophagy-dependent apoptosis in melanoma cells." (PMID 32466337, 2020). "Therefore, in this study, we explored the role of shrimp miR-965 as a natural drug for melanoma therapy by disrupting the MCL-1-ER stress-XBP1 feedback loop in melanoma stem-like cells (MSLC)." (PMID 32586376, 2020). "miR-32, a tumor suppressor miRNA, has recently been demonstrated to suppress the growth of melanoma tumors in preclinical models by inhibiting the expression of the myeloid cell leukemia 1 (MCL-1) gene regulating the RAS-RAF-MEK-ERK and the PI3K-AKT-mTOR pathways." (PMID 32054078, 2020). "Mcl-1 protein level as drug target in amelanotic melanoma cells was determined by Western blotting." (PMID 31432325, 2020). "Moreover, recent studies indicate that reduction of Mcl-1 protein in melanoma cells are necessary and sufficient to induce programmed cell death." (PMID 31432325, 2020). "Malignant melanoma cells exhibit high level and activity of antiapoptotic Mcl-1 protein." (PMID 31432325, 2020). "For example, in melanoma, miR-32 replacement therapy as a single agent has been demonstrated to suppress the growth of melanoma tumors in preclinical models via targeting myeloid cell leukemia 1 (MCL-1) and to exhibit synergistic effects with vemurafenib." (PMID 32258386, 2020). "Melanoma cells exhibit high levels and activity of MCL-1 protein." (PMID 33308268, 2020). "Consistent with this hypothesis, we found that MCL-1 dependence was minimally changed after BRAF inhibition in melanoma cells derived from a patient who was resistant to BRAF/MEK inhibitors." (PMID 31727958, 2019). "Thus, the ratio of the two major pro-survival proteins in solid tumours, MCL1 and BCL-XL, is substantially biased towards MCL1 in melanoma cell lines and patient samples." (PMID 31727888, 2019). "Consequently, E7107 induces preferential cytotoxicity in BCL2A1-high/dependent melanoma cells and MCL1-high/dependent NSCLC cells." (PMID 30635584, 2019). "Indeed, of all the tumour lineages in the CCLE, melanoma exhibited one of the highest median MCL1:BCL-XL mRNA ratios." (PMID 31727888, 2019). "Different antiapoptotic Bcl-2 proteins may substitute each other, and in melanoma cells the particular roles of Bcl-2, Bcl-xL, and Mcl-1 have been described." (PMID 31083589, 2019). "In particular Mcl-1 has emerged as a promising target for the treatment of melanoma." (PMID 31921862, 2019).